IRS2 (insulin receptor substrate 2)
Diseases named in the same sentence as IRS2 in open-access papers (continued):
Sharing a sentence is not in itself a finding about the gene and the disease.
Insulin resistance (continued). "Finally, insulin resistance seen in obesity can lead to compensatory hyperinsulinemia, which in turn can result in increased salt reabsorption from the proximal tubule mediated by insulin receptor substrate 2, whose function is preserved in insulin resistance." (PMID 37418111, 2024). "Furthermore, KA decreased glycerol kinase (GK) expression and increased insulin receptor subtrate 1 (IRS-1) and IRS-2 expressions in the WAT of DIO mice, suggesting that KA partially improved insulin resistance by repairing the impaired insulin signaling pathway caused by DIO." (PMID 38655315, 2024). "Although, how autocrine insulin signaling contributes to β-cell proliferation under any state remains unclear; multiple transgenic mice studies suggest that IRS2 is critical in β-cell hyperplasia in response to insulin resistance, in addition to regulating β-cell mass." (PMID 38201998, 2024). "Rats with MASLD developed insulin resistance, showing increased fasting blood glucose and insulin levels, increased weight of epididymal fat, obvious hepatic steatosis and inflammation and down-regulated IRS-2 mRNA and protein levels compared with normal controls." (PMID 37895151, 2023). "Conversely, downregulating the fatty acid oxidation genes Pnpla2 and Plin2 may promote the formation of intracellular lipid droplets, while downregulating the Irs2 gene may induce insulin resistance and inhibit autophagy in liver cells, ultimately triggering NAFLD." (PMID 37047411, 2023). "Similarly to our observations, decreased SHBG mRNA and protein levels have been previously correlated to lower expression of insulin-associated effectors, namely, IRS-1, IRS-2, PI3Kp85α and GLUT-3 and GLUT-4, and has been further linked to the PI3K/AKT pathway-mediated systemic insulin resistance." (PMID 38146533, 2023). "Finally, given the hyperinsulinemia in response to insulin resistance in Irs2–/–;Cdk4-R24C/R24C, CDK4 may synergize with activation of the unfolded protein response to drive β cell proliferation." (PMID 37712417, 2023). "Because Irs2 function is inhibited by serine phosphorylation and ubiquitin-mediated degradation that is mediated by proinflammatory cytokines, effective management of chronic inflammation might prevent the progression of insulin resistance to diabetes." (PMID 36297523, 2022). "Hence, we offer a compelling insight into the contribution of insulin resistance to the pathogenesis of chronic liver disease and propose IRS2 as a positive regulator of communication between cell types and the transition between phases of stromal to epithelial repair." (PMID 30695023, 2019). "Indeed, myeloid cell-specific Irs2-deficient mice show impairment of IL-4-induced M2a-subtype macrophage activation, as a result of stabilization of the FoxO1/HDAC3/NCoR1 corepressor complex, resulting in insulin resistance under the HF diet condition." (PMID 30451856, 2018). "The expression of the insulin receptor substrate 2 (IRS2) gene could alleviate insulin resistance." (PMID 30403718, 2018). "In insulin resistance, diabetes, and overt diabetic nephropathy, IRS2-dependent stimulation of sodium transport by insulin in the PT is preserved and this may induce sodium retention, whereas IRS1-dependent suppression of gluconeogenesis is attenuated and might induce hyperglycemia." (PMID 27247938, 2016). "ZBPYR could correct CNS insulin resistance by regulating p-IRS2 and p-Akt." (PMID 27393392, 2016). "As previously reported, Irs2-deficient mice displayed elevated levels of both insulin and leptin until the onset of frank diabetes when beta cells are no longer able to compensate for peripheral insulin resistance." (PMID 23741292, 2013). "Although much of the current literature suggests that insulin resistance is an aetiological factor in AD, we have recently demonstrated that mice lacking Irs1 have increased lifespan and reduced age-related pathology and deletion of Irs2 in the mouse brain increases longevity." (PMID 19523444, 2009).
Insulin resistance (continued). "Therefore, chronic hyperinsulinemia in high-salt-fed-Dahl S rats might as well enhance serine phosphorylation on IRS-1 and/or IRS-2 and explain insulin resistance in Dahl S rats." (PMID 18570670, 2008). "Reduced expression of insulin signalling pathway genes in patients with insulin resistance (INSR, AKT, PIK3R1, IRS2) indicates a diminished insulin response in both VAT and SAT." (PMID 40806527, 2025). "The application of sacubitril+valsartan provided an important treatment for insulin resistance due to PCOS by increasing the expression of insulin resistance (IR), insulin receptor substrate 1 (IRS-1), and insulin receptor substrate 2 (IRS-2)." (PMID 41586197, 2025). "For instance, it inhibits the expression of key genes in the insulin signaling pathway, such as IRS-2, PI3K, and Akt, leading to insulin resistance." (PMID 40129979, 2025). "In MASLD, selective insulin resistance develops: IRS-1/lipogenic pathways remain active, while IRS-2/glucose-suppressive pathways are impaired." (PMID 41196673, 2025). "Our data suggest that ATRA mitigates insulin resistance by restoring GLUT4 and IRS-2 expression and dampening macrophage-induced inflammatory signaling." (PMID 41157128, 2025). "Functional enrichment analysis revealed that upregulated genes were involved in PI3K binding (e.g. PIK3IP1, IRS2, ATP1A1), insulin resistance and FOXO signalling genes while downregulated genes were overrepresented by metabolic and immune processes." (PMID 39593143, 2024). "The activation and regulation of SREBP-1c are mediated by insulin receptor substrate 2 (IRS-2), yet in the course of insulin resistance (IR), this receptor is downregulated, thereby leading to the overexpression of SREBP-1c and the intensification of DNL." (PMID 38921480, 2024). "For instance, Diacylglycerol induces insulin resistance through activation of Protein kinase C epsilon type enzyme (PKC-ε) and decreased insulin receptor (IRS-2) tyrosine phosphorylation." (PMID 37759824, 2023). "The results indicated that knocking down PINK1 in hepatic cells reversed the insulin resistance induced by TAC through upregulating the expression of GLUT2 and IRS2/AKT." (PMID 37151651, 2023). "For example, Diacylglycerol induces insulin resistance by activating PKC-ε and reducing IRS-2 tyrosine phosphorylation." (PMID 37759824, 2023). "Hepatitis C virus infection downregulates IRS2 expression by upregulating the suppressor of cytokine signaling (SOCS) and by activating the mTOR/S6K1 signaling pathway, resulting in insulin resistance." (PMID 37670988, 2023). "Knockdown of hepatic PINK1 regulated downstream molecules of the PINK1/Parkin pathway (GLUT2 and IRS2), which reversed TAC-induced insulin resistance." (PMID 37151651, 2023). "Among these pathways, PPARGC1A, CD36, IRS2, PCK2, and IGF1 were enriched in the AMPK signaling pathway, and PCK2 was additionally enriched in the adipocytokine signaling pathway and insulin resistance." (PMID 37958518, 2023). "Another mechanism leading to the development of insulin resistance by overexpression of the SOCS protein was through reduction in the tyrosine phosphorylation of IRS1 and IRS2 required for insulin transduction." (PMID 37529379, 2023). "Insulin resistance is mainly due to the interference in normal insulin signaling by decreasing the expression of insulin receptors, IRS1 and IRS2." (PMID 37014444, 2023). "Other targets of this miRNA are the genes Insulin Receptor Substrate 1 and 2 (IRS1/IRS2) and Insulin-Like Growth Factor 1 (IGF-1), which are closely related to insulin resistance, a characteristic condition of diabetes." (PMID 37511739, 2023). "Hepatic insulin resistance is aggravated by inhibition of physiological phosphorylation of the insulin receptor via the DAG–PKCε pathway and downregulation of hepatic Irs2 expression via hyperinsulinemia." (PMID 33923817, 2021).
Insulin resistance (continued). "Insulin receptor substrate (IRS) 2 is a key mediator of insulin signaling and IRS-2 knockout (IRS2−/−) mice are a preclinical model to study the development of diabetes, as they develop peripheral insulin resistance and beta-cell failure." (PMID 34440853, 2021). "In direct line with their improvement of insulin resistance, HF-fed mice from the n-3 PUFA lineage exhibited a lowered alteration of mitochondrial-related processes and an increased expression of Irs2 in the AT compared to mice from the control lineage." (PMID 34940596, 2021). "SOCS-1 and SOCS-3 induced insulin resistance by inhibiting phosphorylation of insulin receptors IRS-1 and IRS-2 and downstream signaling in mice liver." (PMID 33924165, 2021). "Studies also showed that IR substrate-1 (IRS1) and IR substrate-2 (IRS2) expression were decreased, and the levels of inactivated serine-phosphorylated IRS1 were increased, resulting in insulin resistance in the brain." (PMID 32321934, 2020). "Studies have shown that MET can upregulate the hepatic IRS2/PI3K/Akt signaling pathway, resulting in increased hepatic glycogen storage and improved insulin resistance." (PMID 32256445, 2020). "SOCS3, a known modulator of insulin resistance in the liver, is a protein induced by proinflammatory cytokines that directly inhibits IRS-1/IRS-2 by binding to specific sites, inhibiting phosphorylation and targeting the receptor substrates for degradation." (PMID 32315370, 2020). "Insulin resistance can be monitored by the decreased phosphorylation of two main substrates of the insulin receptor, IRS1 and IRS2." (PMID 30024933, 2018). "Another important finding of the present study is that selective insulin resistance was demonstrated and differential contributions of IRS-1 and IRS-2 were suggested in human NAFLD subjects." (PMID 29717275, 2018). "When applying BAKE to an experimental animal model of insulin resistance progression, we discovered a novel regulatory transcription factor KLF4 to interact with IRS2 and TSC2, two key intermediates in the insulin signaling pathway." (PMID 30240435, 2018). "We confirmed that Ln4 administration induced the up-regulation of hepatic mRNA levels, including IRS2, Akt2, and AMPK, and these results correspond to the data of improving systemic insulin resistance in Ln4-treated mice." (PMID 29783731, 2018). "Based on IRS1 and IRS2 expression in the liver, we aimed to investigate the relationship between NAFLD and impaired glucose metabolism, focusing on hyperinsulinemia, insulin resistance, and postprandial hyperglycemia." (PMID 29749571, 2018). "During insulin resistance in rodents and humans, glucose uptake mediated by IRS1 was severely impaired whereas salt reabsorption in kidney proximal tubule mediated by IRS2 was reserved." (PMID 30602666, 2018). "To investigate the further mechanisms of ADSC transplantation on insulin resistance, we used a q-PCR analysis method to evaluate the expression of insulin resistance-related genes, including IRβ and IRS1, as well as IRS2 and GLUT2 in the liver tissues." (PMID 29258603, 2017). "Both SOCS1 and SOCS3 have been attributed to the development of insulin resistance by inhibiting the phosphorylation of IRS1 and IRS2 proteins." (PMID 29025435, 2017). "On the other hand, it was also demonstrated that lactate induced insulin resistance, and lactate treatment inhibited insulin action by inhibiting the insulin receptor substrate-1 (IRS-1) and IRS-2 mediated PI3K and PKB pathways." (PMID 26938239, 2016). "Insulin resistance is characterized by inability of insulin to exert its signaling effects, mainly due to dysfunction at the level of IRS1 and IRS2 activation and PI3K recruitment to the plasma membrane." (PMID 27434075, 2016).
Insulin resistance (continued). "In addition, considering the fact that the phenotype associated with the lack of Irs2 in the liver was ‘selective insulin resistance', reduced Irs2 expression in the liver may also play a pivotal role in the development of ‘selective insulin resistance'." (PMID 27708333, 2016). "Taking these results together, p38α MAPK mediates the effect of chronic insulin to promote insulin resistance by suppressing IRS1 and IRS2." (PMID 27376265, 2016). "Although mechanisms involved in TNFα-induced insulin resistance are not completely understood, compelling evidence indicates that TNFα inhibits IRS-1- and IRS-2-mediated PI3-kinase activation, leading to insulin resistance." (PMID 26077338, 2015). "Significantly improved insulin resistance by restoring hepatic FOXO1 nuclear translocation and upregulating gene expression of Akt2, Irs1, Irs2, Pi3kca, Pi3kcg and Pdk1." (PMID 25621503, 2015). "On the other hand, following HFD, liver A2bAR is vastly upregulated, resulting in maintenance of adequate levels of IRS-2 and reduced lipids, which are expected to guard against HFD-induced insulin resistance." (PMID 22848385, 2012). "Experimentally, upregulation of SOCS-1 and -3 in the liver leads to insulin resistance through several mechanisms, including degradation of IRS1 and IRS2 inhibition of insulin receptor kinase activity, and downregulation of IFN-associated innate immunity." (PMID 22701799, 2012). "On the other hand, activation of the mTOR pathway via glucose leads to the inhibition of insulin receptor substrate-2 (IRS-2), increase β-cell apoptosis and insulin resistance." (PMID 23227347, 2012). "Activated TNFα inhibits tyrosine phosphorylation of IRS1 and IRS2, and impairs glucose transporter (GLUT)-4 translocation to the cell membrane, leading to insulin resistance and hyperinsulinemia, which can increase glycogenolysis and fatty acid synthesis." (PMID 22701799, 2012). "Furthermore, STA ameliorated insulin resistance, as evidenced by the upregulation of GLUT4 and IRS2 expression and the downregulation of PTP1B and SOCS3 expression." (PMID 40994455, 2025). "Furthermore, it mitigated insulin resistance by upregulating the expression of insulin‐sensitive factors, such as GLUT4 and IRS2, while concurrently downregulating insulin resistance factors, including PTP1B and SOCS3." (PMID 40994455, 2025). "Additionally, PI3K/AKT, through the dephosphorylation of Insulin Receptor Substrate 1 (IRS1) and Insulin Receptor Substrate 2 (IRS2), also counteracts the development of insulin resistance." (PMID 40427436, 2025). "Furthermore, it has been reported that deacetylation of histone H3 lysine 9 (H3K9) via histone deacetylase 6 (HDAC6) leads to suppression of insulin receptor substrate 2 (IRS2) protein, which in turn contributes to the development of insulin resistance." (PMID 40408591, 2025). "For example, in vivo administration of the probiotic Lactobacillus casei CCFM419 has been shown to ameliorate insulin resistance by upregulating phosphatidylinositol-3-kinase (PI3K), insulin receptor substrate 2 (IRS2), AMPK, AKT serine/threonine kinase 2 (Akt2) and glycogen synthesis in the liver." (PMID 39599721, 2024). "Nevertheless, leukocyte IRS2 expression correlated significantly with pregnancy weight, FPG, FI, and HOMA-IR in the GDM subjects, pointing to a linkage of this molecule with adiposity, glucose metabolism, and insulin resistance during diabetic pregnancy." (PMID 39684804, 2024). "In our hepatic insulin resistant mouse model (hepatic insulin receptor substrate 1 (IRS1) and IRS2 double knockout (DKO)), metformin action on glycemic control was impaired, which is largely improved by further deletion of hepatic TGF-β1 (TKObeta1) or hepatic Foxo1 (TKOfoxo1)." (PMID 38397103, 2024).
Insulin resistance (continued). "With respect to IRS2, we found that its expression pattern was similar in the leukocytes of the GDM women during and after pregnancy, consistent with what has previously been shown in leukocytes of individuals with insulin resistance." (PMID 39684804, 2024). "In the context of obesity and type 2 diabetes, metabolic and inflammatory stress increase the activities of JNK and ERK in insulin target tissues, and these kinases induce serine phosphorylation of IRS1 or IRS2, whereas uncontrolled IRS serine phosphorylation promotes insulin resistance." (PMID 37108143, 2023). "It has been reported that mice with Irs2 gene knockout exhibited selective insulin resistance, while mice lacking Irs1 or Irs1 and Irs2 developed total insulin resistance." (PMID 36982617, 2023). "Hepatic steatosis or hepatic fat infiltration may induce hepatic insulin resistance through activation of JNK1 and PKC-epsilon, which may interfere with tyrosine phosphorylation of IRS-1 and IRS-2." (PMID 35968500, 2022). "We described that miR-7, which is itself regulated by insulin, impairs insulin signaling and could lead to insulin resistance in the brain through the post-transcriptional regulation INSR, IRS-2." (PMID 36010613, 2022). "Thus, genes in the insulin signalling pathway, such as the insulin receptor (INSR), insulin receptor substrates 1 and 2 (IRS1 and IRS2), and GLUT4, are attractive candidates for insulin resistance." (PMID 35627115, 2022). "Since hepatic Irs2 mRNA levels have been reported to be actually lower in NAFLD patients, downregulated Irs2 might be involved in the pathogenesis of hepatic insulin resistance." (PMID 33923817, 2021). "Insulin resistance signaling is an exclusively mediated by IRS1 and IRS2 in the liver." (PMID 34449768, 2021). "By their ability to promote ubiquitination and proteasomal degradation of insulin receptor substrates 1 and 2 (IRS1, IRS2), which link RTK signaling to PI3K, SOCS1 and SOCS3 can regulate AKT activation in the context of insulin resistance in the liver and other organs." (PMID 32807134, 2020). "Insulin resistance–metabolic syndrome patients have been reported to benefit from strategies concerning stimulation of VSMC survival and reduction in FKN/CX3CR1 signaling to promote plaque stability through an IRS2-dependent signaling." (PMID 32532282, 2020). "Simultaneous deletion of IRS1 and IRS2 genes in the liver of mice could inhibit the phosphorylation cascade of AKT, leading to hyperglycemia, hyperinsulinemia, and insulin resistance." (PMID 32280711, 2020). "Hyperinsulinemia that observed in T2DM and T2DM_CAD groups, may down regulate IRS1 and IRS2 via p38-MAPK and triggers insulin resistance in liver and skeletal muscle." (PMID 30674322, 2019). "Thus, we demonstrated that short-term exposure to 10 ng/ml TNFα induces reversible downregulation of IRS2 and eNOS due to EndMT-like differentiation and it is also likely to induce irreversible GM1 expression, probably resulting in chronic insulin resistance." (PMID 29464018, 2018). "Mice lacking IRS2 show insulin resistance and beta-cell failure, resulting in peripheral insulin resistance and DM2 after 8–10 weeks of age." (PMID 29628894, 2018). "Mice lacking the insulin receptor substrate 1 (IRS1−/−) but not IRS2 (IRS2−/−) are long-lived, but strangely have lifelong insulin resistance, while being also resistant against age-sensitive markers." (PMID 28768896, 2017). "NAFLD or liver fatty infiltration may induce hepatic insulin resistance by activating PKC-epsilon and JNK1, which may interfere with the tyrosine phosphorylation of IRS-1 and IRS-2." (PMID 29051770, 2017). "Along with the decrease in the phosphorylation of insulin receptor substrates (IRS-1 and IRS-2) and in PI3-K activity observed in insulin resistance, the translocation of glucose transporters and the activity of key enzymes implicated in glucose homeostasis are also reduced." (PMID 28259166, 2017).